DCAF12L1 (DDB1 and CUL4 associated factor 12 like 1)
Synonyms: WDR40B; KIAA1892L
Tractability: No criterion of Open Targets' tractability assessment is met for any kind of drug.
Gene: Protein-coding gene on chromosome X (126,549,383 to 126,552,814, reverse strand). Ensembl gene ENSG00000198889.
Subcellular location (Human Protein Atlas): Cytosol
Gene Ontology:
Molecular function: protein binding
Cellular component: Cul4-RING E3 ubiquitin ligase complex
Homologues: Orthologues: chimpanzee DCAF12L1 (97% identical), macaque DCAF12L1 (96% identical). Paralogues in human: DCAF12L2 (87% identical), DCAF12 (61% identical).
Diseases named in the same sentence as DCAF12L1 in open-access papers:
DCAF12L1 is named in the same sentence as 5 diseases in open-access papers, as found by Europe PMC text mining. Sharing a sentence is not in itself a finding about the gene and the disease. The quoted sentences say what the papers report.
clear cell carcinoma (1 paper, 2020).
depression (1 paper, 2019). "Furthermore, the expression levels of Plin4, Sgk1 and Klf2 increased in the striatum samples of rat models of depression following administration of ketamine, and the expression of Dcaf12l1 decreased compared with the control group." (PMID 31281445, 2019). "The FoxO and mTOR signaling pathways may be involved in the underlying mechanism of the antidepressant effects of ketamine, and Plin4, Sgk1, Klf2 and Dcaf12l1 may be potential biomarkers for depression in N-methyl-D-aspartic acid receptor antagonist treatment." (PMID 31281445, 2019). "The current study indicated that Plin4, Sgk1, Klf2 and Dcaf12l1 were differentially expressed in depression models treated with ketamine, phencyclidine and memantine, which suggested that these genes may be the targets of the NMDA receptor antagonist treatment." (PMID 31281445, 2019).
infection (2 papers, 2020 to 2024). The state of being infected such as from the introduction of a foreign agent such as serum, vaccine, antigenic substance or organism. "DCAF12L1 targeted proteins involved in mRNA splicing, transcription, and chromatin regulation, with increased associations during infection." (PMID 39383947, 2024). "Moreover, multiple mechanisms related to ubiquitination-induced degradation of proteins associated with DCAF12L1 are lost upon infection, in line with the observed release of proteasome from DCAF12L1." (PMID 39383947, 2024). "Conversely, DCAF12L1 gains cellular interactors upon infection, with 143 only in infected cells compared to 48 proteins associated exclusively in non-infected cells." (PMID 39383947, 2024). "Our results are consistent with a modified repertoire of active CRL4 E3 ligases upon IAV infection, with those using DCAF12L1 as an SRF gaining a prevailing effect in CRL4-mediated ubiquitination that serves infection." (PMID 39383947, 2024). "We detected the association of DCAF12L1 with CRL4 E3 ligase components and ribosomal proteins, with minor changes upon infection." (PMID 39383947, 2024). "We also identified an association of DCAF12L1 with the proteasome and CSN complexes, with multiple subunits lost upon infection." (PMID 39383947, 2024). "Among these, 25 of the 73 infection-specific (34%) and 10 of the 26 infection-free specific factors (38.4%) are directly bound to DCAF12L1." (PMID 39383947, 2024). "Different binding profiles emerged, with the number of associated partners decreasing upon infection for DDB1 and DCAF11, while DCAF12L1 gained interactors." (PMID 39383947, 2024). "To assess the functional relevance of our datasets, we first conducted literature mining to determine the role of 41 host proteins that differentially interacted with either DCAF11 or DCAF12L1 upon infection." (PMID 39383947, 2024). "Additionally, 23 factors maintained their association with DCAF12L1 independent of infection, including UPS factors and regulators, proteins involved in translation and folding, and RNA processing." (PMID 39383947, 2024). "Infection-induced alterations in the binding profiles of DCAF11 and DCAF12L1 targeted common cellular processes, including translation, RNA metabolism, and transcription, all intricately regulated through ubiquitination." (PMID 39383947, 2024). "A significant rewiring of the CRL4s interaction partners was observed, particularly for DDB1 for which only 26% of the 119 interactors remained constant upon infection, whereas 49% and 65% remained unchanged for DCAF11 and DCAF12L1, respectively." (PMID 39383947, 2024). "Our results revealed substantial modulations in the interaction networks of the three factors, DDB1, DCAF11, and DCAF12L1, characterized by a comprehensive reduction in DDB1 and DCAF11 interactions, while DCAF12L1 interactors increased upon infection." (PMID 39383947, 2024). "Such interactions could mediate the ubiquitination and degradation of RNA polymerase II via the proteasome pathway occurring at late stages of infection, and CRL4 DCAF12L1 E3 ligases may be involved in such heretofore undiscovered activity." (PMID 39383947, 2024). "Interestingly, such association decreased upon infection for DDB1 and DCAF12L1, suggesting a shift towards non-proteolytic ubiquitination, consistent with our previous findings on PB2 ubiquitination." (PMID 39383947, 2024). "Additionally, we observed an increased proportion of factors interacting only with DCAF12L1 in the infection compared to the non-infected condition." (PMID 39383947, 2024). "Such GO-term enrichment supports our previous proposals that (i) DCAF12L1 might be the preferred SRF of CRL4s during infection, (ii) the CRL4s-mediated ubiquitination might be shifted toward non-proteolytic, proteasome independent ubiquitination under infection." (PMID 39383947, 2024).
tumor (1 paper, 2023). "Several studies have indicated that the seven key prognostic genes identified in this study for UCEC, including TSPYL5, VNN2, ANXA1, and DCAF12L1, are associated with tumor occurrence and development." (PMID 37363398, 2023).
DCAF12L1 also shares sentences with these, for which no sentence is quoted: polycystic ovary syndrome (1 paper).